SLC5A8 (solute carrier family 5 member 8)
Description:
Acts as an electrogenic sodium (Na(+)) and chloride (Cl-)- dependent sodium-coupled solute transporter, including transport of monocarboxylates (short-chain fatty acids including L-lactate, D-lactate, pyruvate, acetate, propionate, valerate and butyrate), mocarboxylate drugs (nicotinate, benzoate, salicylate and 5-aminosalicylate) and ketone bodies (beta-D-hydroxybutyrate, acetoacetate and alpha-ketoisocaproate), with a Na(+):substrate stoichiometry of between 4:1 and 2:1. Catalyzes passive carrier mediated diffusion of iodide. Mediates iodide transport from the thyrocyte into the colloid lumen through the apical membrane. May be responsible for the absorption of D-lactate and monocarboxylate drugs from the intestinal tract. Acts as a tumor suppressor, suppressing colony formation in colon cancer, prostate cancer and glioma cell lines. May play a critical role in the entry of L-lactate and ketone bodies into neurons by a process driven by an electrochemical Na(+) gradient and hence contribute to the maintenance of the energy status and function of neurons. Mediates sodium-coupled electrogenic transport of pyroglutamate (5-oxo-L-proline). Can mediate the transport of chloride, bromide, iodide and nitrate ions when the external concentration of sodium ions is reduced. Part of D-serine transport systems. May contribute to D-serine reabsorption at the brush border of renal proximal tubules thus modulating the dynamics of urinary versus blood D-serine levels.
Synonyms: AIT; SMCT; SMCT1
Tractability: Small molecule: a structure with a bound ligand is known. Antibody: UniProt places it where antibodies can reach, with high confidence; its Gene Ontology location is reachable by antibodies, with high confidence; UniProt predicts a signal peptide or a membrane-spanning region.
Gene: Protein-coding gene on chromosome 12 (101,155,493 to 101,210,238, reverse strand). Ensembl gene ENSG00000256870.
Subcellular location: Apical cell membrane
Pathways (Reactome):
Transport of small molecules: Organic anion transport by SLC5/17/25 transporters; SLC-mediated transport of inorganic anions
Metabolism: Nicotinate metabolism
Gene Ontology:
Molecular function: monocarboxylate:sodium symporter activity; protein binding; iodide channel activity; monocarboxylic acid transmembrane transporter activity; organic acid:sodium symporter activity; lactate transmembrane transporter activity; nicotinate transmembrane transporter activity; propionate transmembrane transporter activity; short-chain fatty acid transmembrane transporter activity; solute:sodium symporter activity; transmembrane transporter activity
Biological process: acetate transport; chloride transport; iodide transport; lactate transport; nicotinate transport; nitrate transmembrane transport; propanoate transmembrane transport; pyruvate transport; nicotinate metabolic process; sodium ion transport; transmembrane transport; lactate transmembrane transport; sodium ion transmembrane transport
Cellular component: apical plasma membrane; extracellular exosome; plasma membrane; GINS complex; membrane
Genetic constraint (gnomAD): Loss-of-function variants: 47 observed, 60.52 expected, observed/expected ratio (o/e) 0.78, 90% interval 0.61 to 0.99. The upper end of that interval is the gene's LOEUF score, 0.99, which puts it in group 4 of 6, group 1 being the genes least tolerant of losing a copy. Missense variants: 650 observed, 715.44 expected, observed/expected ratio (o/e) 0.91, 90% interval 0.85 to 0.97. Synonymous variants: 284 observed, 269.85 expected, observed/expected ratio (o/e) 1.05, 90% interval 0.95 to 1.16.
Homologues: Orthologues: chimpanzee SLC5A8 (99% identical), macaque SLC5A8 (98% identical), dog SLC5A8 (90% identical), pig SLC5A8 (90% identical), rat Slc5a8 (87% identical), mouse Slc5a8 (87% identical), rabbit SLC5A8 (85% identical), guinea pig SLC5A8 (82% identical), tropical clawed frog slc5a8 (75% identical), zebrafish slc5a8 (57% identical), Drosophila melanogaster Smvt (33% identical), Drosophila melanogaster bumpel (32% identical), and 10 more. Paralogues in human: SLC5A12 (52% identical), SLC5A5 (48% identical), SLC5A6 (43% identical), SLC5A9 (23% identical), SLC5A2 (22% identical), SLC5A1 (22% identical), SLC5A4 (22% identical), SLC5A11 (22% identical), SLC5A10 (21% identical), SLC5A3 (21% identical), SLC5A7 (18% identical).
Diseases named in the same sentence as SLC5A8 in open-access papers:
SLC5A8 is named in the same sentence as 59 diseases in open-access papers, as found by Europe PMC text mining. Sharing a sentence is not in itself a finding about the gene and the disease. The quoted sentences say what the papers report.
colon cancer (14 papers, 2005 to 2025). "In colon cancer, a proteomic study suggested a causative role of SLC5A8, that downregulation of SLC5A8 is an early event in carcinogenesis, and that a low protein level is a marker of poor prognosis." (PMID 40869209, 2025). "In this study, we established the methylation status of SLC5A8 in colon adenomas in African Americans, a population at high risk of developing colon cancer." (PMID 21687703, 2011). "Recently, a number of tumor-related genes were found to be aberrantly methylated in association with the MAPK pathway overactivated by BRAF mutation in human cancers, such as hMLH1 in colon cancer, and SLC5A8 in thyroid cancer." (PMID 21507233, 2011). "It is notable that SLC5A8, a gene that encodes a monocarboxylic acid transporter protein, has been reported to be a tumor suppressor gene in colon cancer and other cancers." (PMID 16153295, 2005). "Additional confirmation of the tumor-suppressive function of SLC5A8 was indicated by the fact that re-expression of SLC5A8 leads to the suppression of colony formation in colon cancer cell lines." (PMID 40869209, 2025). "The silencing mechanism is attributed to DNA methylation of the SLC5A8 promoter in both primary tumours and human colon cancer cell lines." (PMID 40181975, 2025). "SLC5A8, a conditional tumour suppressor, has been shown to have a protective effect against colitis and colon cancer in the context of a low-fibre diet." (PMID 40181975, 2025). "Re-expression of SLC5A8 in colon cancer cells induces cell death, which is consistent with the characteristics of a tumour suppressor gene." (PMID 40181975, 2025). "It has also been observed that SLC5A8 can prevent colitis and colon cancer under conditions of low fiber intake." (PMID 39061538, 2024). "In colon cancer cells, the gene slc5a8 was found to be silenced via DNA methylation modifications; when re-expressed, slc5a8 can cause tumor cell growth arrest and apoptosis." (PMID 34203243, 2021). "For example, SLC5A8 is silenced by methylation in human astrocytomas and oligodendrogliomas and in primary colon cancers and colon cancer cell lines." (PMID 24653705, 2014). "As such, we here propose to analyze the methylation status of SLC5A8 gene in African American colon adenomas with the goal of finding early colon cancer markers in this group of patients to mitigate the high incidence of the disease in this group." (PMID 21687703, 2011). "The high level of SLC5A8 methylation in our study also fits the general picture about genes' methylation in AA colon cancer." (PMID 21687703, 2011). "SLC5A8 is silenced by methylation in most human colon tumors and reintroduction of this gene leads to growth suppression." (PMID 15882471, 2005). "Interestingly, inhibiting DNA methylation leads to an increase in the expression of SLC5A8 in colon cancer cells." (PMID 40181975, 2025). "As with SLC5A8, GPR109A may also undergo DNA methylation in colon cancer, but GPR109A can be re-expressed in colon cancer cells in the presence of butyrate, leading to the death of tumor cells." (PMID 34203243, 2021).
thyroid cancer (10 papers, 2011 to 2025). "Our COX multivariate analysis showed that SLC5A8 methylation is one of the risk factors affecting the prognosis of thyroid cancer." (PMID 38007446, 2023). "Human thyroid cancer cell lines exhibit barely detectable levels of SLC5A8, similarly to the tumor tissue." (PMID 40869209, 2025). "The methylation profile of thyroid cancer exhibits a specific signature according to the histological subtype, and the predictive potential of DNA methylation, especially of SLC5A8, for thyroid cancer prognosis remains to be further explored." (PMID 38007446, 2023). "Previous evidence suggests that SLC5A8 alleviates disease progression by regulating the Wnt signaling pathway, which requires further exploration in patients with thyroid cancer." (PMID 38007446, 2023). "Solute carrier family 5 (sodium/monocarboxylate cotransporter), member 8(SLC5A8) is a sodium-transporting protein that inhibits various solid tumors through methylation and has been observed in colon, stomach, lung, brain, and thyroid cancers." (PMID 34923978, 2021). "We recently conducted a meta-analysis the results of which indicated that SLC5A8 was the most significant methylated gene in thyroid cancers." (PMID 31754358, 2019). "In a panel of analyzed tumor suppressors, promoter hypermethylation of CDH1, p16INK4A, RASSF1A and SLC5A8 in malignant thyroid tumors was confirmed." (PMID 25490036, 2014). "The reasons for the deregulation of SLC5A8 in differentiated thyroid carcinomas are largely unknown." (PMID 40869209, 2025). "Detection of SLC5A8 methylation has also been reported, which may contribute to the early diagnosis and prognosis of thyroid cancers." (PMID 38007446, 2023). "Our study reported that the SLC5A8 methylation positivity rate was associated with high thyroglobulin and cholesterol levels, which may suggest that dysregulation of the SLC5A8 gene is involved in widespread metabolic disturbances in patients with thyroid adenoma and thyroid cancer." (PMID 38007446, 2023). "It was shown that SLC5A8 expression, as a sodium/iodide symporter (NIS) member, decreased in several malignancies, including thyroid cancers and its methylation is shown as the discriminative marker between malignant and benign thyroid tumors." (PMID 31754358, 2019). "The differences in SLC5A8 methylation and expression among FTA, FTC, and TT-UMP provide an important basis for further exploration of epigenetic changes in the occurrence, development, and prognosis of thyroid cancer." (PMID 38007446, 2023).
gastric cancer (7 papers, 2009 to 2023). A primary or metastatic malignant neoplasm involving the stomach. "SLC5A8 (solute carrier family 5, member 8) is a tumor suppressor gene and is usually suppressed in colon, and gastric cancers." (PMID 25657825, 2015). "Although decreased SLC5A8 expression has been reported among individuals with gastric cancer, it has not been directly associated with H. pylori infection in adults or in children with symptomatic or asymptomatic infection." (PMID 27777899, 2016). "Conversely, the levels of the tumor suppressors (e.g., DAPK1, TIMP3, GRIN2B, SLC5A8, and CDH1) are low in the gastric tissues of patients with gastric cancer." (PMID 35211104, 2022). "SLC5A8 and SLC16A1 have been purported to provide a mechanism for the suppression of tumour growth in colorectal and gastric cancers and are down-regulated with tumour progression." (PMID 19689820, 2009).
cervical cancer (5 papers, 2019 to 2025). A primary or metastatic malignant neoplasm involving the cervix. "SLC5A8 is a tumor-suppressive transporter in cervical cancer (CC), and its overexpression suppresses proliferation and induces apoptosis by inhibiting Wnt signaling and arresting HeLa cells at the G1 phase." (PMID 40548257, 2025). "Consistent with our finding, down-regulated mRNA expression of SLC5A8 was reported in cervical cancer, hepatocellular carcinoma, and Helicobacter pylori infection." (PMID 38007446, 2023). "The biological behavior of SLC5A8 in cervical cancer has been reported, which can alleviate the progression of cervical cancer by regulating the Wnt signaling pathway." (PMID 35456426, 2022). "Moreover, we identified four cervical cancer-specific methylation markers, cg07211381 (RAB3C), cg12205729 (GABRA2), cg20708961 (ZNF257), and cg26490054 (SLC5A8), with 96.2% sensitivity and 95.2% specificity by using the tenfold cross-validation of TCGA data." (PMID 31871774, 2019). "We identified four cervical cancer-specific methylation markers, including cg07211381 (RAB3C), cg12205729 (GABRA2), cg20708961 (ZNF257), and cg26490054 (SLC5A8), and the significantly decreased expression of GABRA2, ZNF257, and SLC5A8 in CSCC was further confirmed in human CSCC tissues by IHC." (PMID 31871774, 2019).
colitis (4 papers, 2019 to 2025). Inflammation of the colon. "As the fiber content in the diet and the SCFA transporter Slc5a8 are principally associated with colonic inflammation, we focused on colitis while analyzing the transcriptome profiles by IPA." (PMID 31976310, 2019). "We found that deletion of Slc5a8 itself causes alterations of gene expression that is conducive for colitis, and deficiency of fiber in the diet exacerbates this phenomenon." (PMID 31976310, 2019). "This pathway protects against colitis, but its activity is decreased in Slc5a8-null mice independent of fiber content in the diet." (PMID 31976310, 2019).
glioma (4 papers, 2022 to 2025). A benign or malignant brain and spinal cord tumor that arises from glial cells (astrocytes, oligodendrocytes, ependymal cells). "The monocarboxylate co-transporter (SLC5A8) is an oncosuppressor of human and experimental gliomas, encoded by SLC5A8, and its activity depends on the intracellular Na+ and Cl− content." (PMID 40725030, 2025). "The SLC5A8 is expressed in normal brain cells but is significantly reduced in most human glioma primary cells and cell lines, especially when the associated CpG islands were aberrantly methylated." (PMID 39061990, 2024). "The transport function of SLC5A8 is particularly significant in brain tumors, as butyrate and dichloroacetate are currently being investigated for treating human gliomas." (PMID 39061990, 2024). "SLC5A8 is a tumor growth suppressor in experimental animals and primary human gliomas that contributes to carcinogenesis and is repressed by epigenetic mechanisms." (PMID 39061990, 2024). "Ectopic expression of SLC5A8 strongly inhibits colony formation in glioma cell lines, indicating that it suppresses glioma growth in vitro." (PMID 39061990, 2024). "SLC5A8 is a tumor growth suppressor in primary human and experimental animal gliomas that contributes to carcinogenesis and is repressed by epigenetic mechanisms." (PMID 39061990, 2024). "The SLC5A8 acts as a tumor growth suppressor gene, often silenced by epigenetic mechanisms in primary gliomas." (PMID 35625705, 2022). "SLC5A8 is a tumor growth-inhibitory gene in primary human and experimental animal glioma and is suppressed by epigenetic mechanisms." (PMID 35625705, 2022). "Downregulation of SLC5A8 is related to the process of carcinogenesis and was reported in colon, thyroid, prostate, pancreas, squamous cell head, neck, breast, lung, and cervical cancers, as well as in gliomas and acute myeloid leukemia." (PMID 40869209, 2025).
pancreatic cancer (4 papers, 2013 to 2021). "assessed the effect of SLC5A8 expression on the survival outcomes of patients with pancreatic cancer and found that low expression and nuclear translocation of SLC5A8 were associated with a poor prognosis." (PMID 33783998, 2021). "SLC5A8 is another tumor suppressor gene, which is often downregulated by promoter hypermethylation in pancreatic cancer." (PMID 31612869, 2019). "For example, SLC5A8 was identified as a tumor suppressor gene that is frequently down-regulated by promoter hypermethylation in prostate tumors and pancreatic cancer." (PMID 25749033, 2015).
adenoma (3 papers, 2011 to 2018). A neoplasm arising from the epithelium. "However and since BRAF mutation seems to associate with SLC5A8 methylation in this group of adenomas, it would be unlikely." (PMID 21687703, 2011). "Our exclusive choice to work with adenomas, and our inclusion of 5 polyps in this study strengthen that assumption and qualify SLC5A8 gene as a potential marker for early detection in this high risk group of patients." (PMID 21687703, 2011). "We performed immunohistochemistry on several adenomas using an antibody that is specific to SLC5A8 protein (provided by as a gift by V. Ganapathy)." (PMID 21687703, 2011). "The analyzed samples displayed 82% (n = 41) methylation level of SLC5A8 gene in adenomas." (PMID 21687703, 2011). "However, there were more right sided adenomas with SLC5A8 methylation than the left sided ones." (PMID 21687703, 2011). "Most of the studies on SLC5A8 were done on cancer samples and none has checked in adenomas." (PMID 21687703, 2011).
breast cancer (3 papers, 2017 to 2019). A primary or metastatic malignant neoplasm involving the breast. "Since a CRC cell line expressing a functional SLC5A8 was unavailable, we sought to determine the effect of 2,4,6-THBA on a breast cancer cell line (MDA-MB-231) previously characterized and reported to express this protein under the control of the tet-promoter (SLC5A8-pLVX)." (PMID 30917530, 2019). "SLC5A8 is silenced in many cancer tissues as well as in mammary cancer, so that DCA might not accumulate in mammalian cells and apoptosis was not induced with 1 mM DCA." (PMID 28591165, 2017).
colorectal cancer (3 papers, 2009 to 2024). A primary or metastatic malignant neoplasm that affects the colon or rectum. "The tumor-suppressor role played by SLC5A8 in colorectal cancer is one example of a known mechanism." (PMID 38366023, 2024). "In addition, restoration of the pyruvate transporter SLC5A8 in colorectal cancer cells sensitizes them to pyruvate-induced apoptosis whereas pyruvate administration restored the cytotoxic effects of doxorubicin, 5-fluorouracil, and oxaliplatin in otherwise chemo-resistant cancer cells." (PMID 33230593, 2021). "When the data were combined, a combination of MMP-7 and SLC5A8 (and, to a lesser extent, RECK) provided the greatest separation between healthy colon tissue and colorectal cancer (tissue or cell lines)." (PMID 19689820, 2009). "In contrast to SLC5A8, SLC25A22 reportedly plays a tumor-promoter role in colorectal cancer." (PMID 38366023, 2024).
glioblastoma (3 papers, 2022 to 2024). The most malignant astrocytic tumor (WHO grade IV). "The study aimed to determine the expression of carcinogenesis-related SLC5A8, SLC12A2, SLC12A5, CDH1, and CDH2 in adult glioblastoma U87 MG and T98G cells and the effects of 0.5 mM, 0.75 mM, and 1.5 mM doses of VPA." (PMID 39061990, 2024). "This study aimed to investigate the effect of VPA on the expression of the NKCC1, KCC2, and SLC5A8 co-transporters genes and the CDH1 and CDH2 genes in adult glioblastoma U87 MG (female) and T98G (male) cells." (PMID 39061990, 2024). "This study aimed to investigate the effect of 0.5 and 0.75 mM VPA on NKCC1 (SLC12A2), KCC2 (SLC12A5) and SLC5A8 (SLC5A8) co-transporter gene expressions in pediatric PBT24 (boy’s) and SF8628 (girl’s) glioblastoma cells." (PMID 35625705, 2022). "The different effects of VPA on the expression of SLC12A2, SLC12A5, and SLC5A8 in PBT24 and SF8628 glioblastoma cells suggest differences in tumor cell biology." (PMID 35625705, 2022). "The distinct effects of VPA on the expression of SLC12A2, SLC12A5 and SLC5A8 in PBT24 and SF8628 glioblastoma cells suggest differences in tumor cell biology that may be gender-related." (PMID 35625705, 2022).
head and neck squamous cell carcinoma (3 papers, 2012 to 2019). A squamous cell carcinoma that arises from any of the following anatomic sites: lip and oral cavity, nasal cavity, paranasal sinuses, pharynx, larynx, and salivary glands. "In contrary, the overexpression of SLC5A8 together with IRX1 and EBF3 may be involved in the transforming growth factor beta signaling pathway, which is often disrupted in head and neck squamous cell carcinoma." (PMID 31754358, 2019).